RBM15 (RNA binding motif protein 15)
Diseases named in the same sentence as RBM15 in open-access papers (continued):
Sharing a sentence is not in itself a finding about the gene and the disease.
myeloproliferative disease (1 paper, 2012). "Consistent with this hypothesis, introduction of a constitutively active form of the Mpl receptor into bone marrow cells cooperates with Rbm15-Mkl1 and leads to myeloproliferative disease with a high frequency." (PMID 22927943, 2012).
osteoporosis (1 paper, 2023). A condition of reduced bone mass, with decreased cortical thickness and a decrease in the number and size of the trabeculae of cancellous bone (but normal chemical composition), resulting in increased fracture incidence. "Existing studies have confirmed that RBM15 in stress hematopoiesis have a variety of aging-related physiologic changes, including increased DNA damage and NF-κB activation, which may serve as important pathological factors in the development of osteoporosis." (PMID 36967763, 2023). "In addition, study has reported that knockdown of RBM15 and RBM15B impairs XIST-mediated gene silencing, which influences osteoblast differentiation in osteoporosis." (PMID 36967763, 2023).
placental insufficiency (1 paper, 2024). Failure of the placenta to deliver an adequate supply of nutrients and oxygen to the fetus. "More importantly, a previous in vivo study determined that the knockdown of RBM15 led to defects in the morphology of placental vascular branches within the syncytiotrophoblast and spongy trophoblast cell layers that play an essential role in placental insufficiency and cardiac malformation." (PMID 38765115, 2024).
rectal cancer (1 paper, 2021). A primary or metastatic malignant neoplasm that affects the rectum. "In the univariate cox analysis, RBM15, YTHDF2, and METTL14 were significantly correlated with prognosis in rectal cancer patients." (PMID 34221955, 2021).
retinoblastoma (1 paper, 2013). A malignant tumor that originates in the nuclear layer of the retina. "Within the recurrent focal gains or losses in the RbTKO retinoblastoma model, we found 12 in cancer genes, including Lmo1 in 5/6 samples; Ndrg1, Brd4, Fbxo11, and Rbm15 in 4/6 samples; Mdm4, Msi2, and Ezh2 in 3/6 samples." (PMID 23765217, 2013).
steatosis (1 paper, 2022). Increased lipid within the cytoplasm of cells. "RBM15, YTHDC2, HNRNPC, HNRNPA2B1, and EIF3H were related to steatosis." (PMID 36120320, 2022).
synovial sarcoma (1 paper, 2024). "On the other hand, the expression of RBM15 and FMR1 was significantly downregulated in synovial sarcoma tissue, suggesting they might have an important role in tumor suppression." (PMID 38549939, 2024).
uterine corpus endometrial carcinoma (1 paper, 2023). A endometrial carcinoma (disease) that involves the body of uterus. "In the TIMER2.0 database, there was a positive association between RBM15 and CD4 + T-cell infiltration in uterine corpus endometrial carcinoma (CESC), but the correlation coefficient was only 0.156." (PMID 37474926, 2023).
tumor (102 papers, 2020 to 2026). "In vivo, RBM15 loss significantly delays tumor progression and enhances CD8+ T cell infiltration and activation within the TME." (PMID 41403702, 2025). "As a critical regulator of m6A modification, RBM15 influences tumor-associated gene expression not only through m6A-dependent mechanisms but also via m6A-independent pathways of post-transcriptional regulation." (PMID 41403702, 2025). "Silencing ITGBL1 inhibits proliferation, migration, invasion, M2 macrophage polarization, and CD8+ T cell immunosuppression, while RBM15 deficiency significantly reduces tumor growth." (PMID 41403702, 2025). "In contrast, there were limited differences in tumor weight between Rbm15-KO cells and WT cells in immunodeficient nude mice, suggesting that the reduced tumor growth caused by Rbm15 deficiency mainly attributed to the induction of anti-tumor immunity." (PMID 40370450, 2025). "RBM15/TNFSF9 induced M2 polarization of tumor-associated macrophages and enhanced paclitaxel resistance in TNBC." (PMID 40830812, 2025). "The correlation between RBM15 expression and clinical characteristics was then assessed, showing a significant association with tumor size and tumor-node-metastasis (TNM) stage." (PMID 39716068, 2024). "This is consistent with previous studies, which found that high expression of RBM15 is significantly associated with tumor progression and poor prognosis in a variety of cancers, including LSCC, COAD, LIHC, and PAAD." (PMID 36232485, 2022). "High expression of RBM15 is associated with poor prognosis and tumor immunity in many cancers, especially in PAAD." (PMID 35223996, 2022). "Results showed RBM15 expression was significantly correlated with the mutation levels of MMR genes in most tumor types." (PMID 35223996, 2022). "RBM15 deficiency restrains tumor growth by enhancing immune cell infiltration." (PMID 40370450, 2025). "Moreover, RBM15 is significantly overexpressed in LC, which leads to increased tumor volume and invasion and is associated with poor prognosis of patients." (PMID 39039611, 2024). "The effect of the RBM15/m6A/SRSF1/ATP7B axis on tumor growth was evaluated using tumor xenografts in nude mice." (PMID 40923717, 2026). "Functionally, RBM15 overexpression reduces PCa cell sensitivity to enzalutamide, whereas its knockdown suppresses tumor growth and invasion." (PMID 41949706, 2026). "RBM15 knockdown impedes tumor growth via XPR1 regulation, underscoring the oncogenic role of the RBM15/XPR1 axis in LUAD." (PMID 41403702, 2025). "This inhibits cuproptosis and enhances tumor cell proliferation and invasion, while RBM15 inhibition triggers cuproptosis and suppresses tumor growth." (PMID 41403702, 2025). "Functional studies demonstrated that RBM15 knockdown suppresses CC cell proliferation, migration, and invasion, as well as tumor growth in vivo." (PMID 41403702, 2025). "In triple-negative breast cancer, RBM15 facilitates tumor growth by enhancing serine and glycine metabolism." (PMID 41256854, 2025). "This knowledge gap limits the development of RBM15-based immunotherapeutic strategies and underscores the need for further mechanistic studies in tumor immunology." (PMID 41403702, 2025). "Elevated KLF1 or reduced TRIM13 can partially offset the inhibitory effects caused by RBM15 depletion, while ANXA8 overexpression diminishes the tumor-suppressive impact of RBM15 silencing on malignant behaviors." (PMID 41403702, 2025). "Beyond its tumor-intrinsic effects, RBM15 influences the tumor immune microenvironment by affecting immune cell differentiation, activation, and cytokine production, thereby contributing to immune evasion." (PMID 41403702, 2025). "In summary, this study identifies a cancer cell-intrinsic mechanism by which RBM15 acts as a suppressor of anti-tumor immune responses through metabolic rewiring." (PMID 40370450, 2025).
tumor (continued). "The xenograft tumor models in nude mice were established to verify the impact of RBM15/TNFSF9 on the sensitivity of PTX-resistant TNBC cells to PTX in vivo." (PMID 40830812, 2025). "In contrast, this review aims to systematically summarize recent advances regarding the roles of RBM15 in cancer progression and tumor immunity, with a particular emphasis on its m6A-mediated molecular mechanisms and potential clinical applications." (PMID 41403702, 2025). "RBM15 is consistently upregulated, and its silencing markedly suppresses CC cell proliferation, migration, invasion, and tumor formation." (PMID 41403702, 2025). "RBM15, a key RNA-binding protein involved in m6A RNA methylation, plays multifaceted roles in cancer development and tumor immunity." (PMID 41403702, 2025). "First, studies investigating the role of RBM15 in tumor immunity are still limited, which makes the discussion on its immunoregulatory mechanisms relatively insufficient." (PMID 41403702, 2025). "This study demonstrated that RBM15 enhanced PTX resistance in TNBC by promoting m6A methylation in TNFSF9 and inducing M2 polarization of tumor-associated macrophages." (PMID 40830812, 2025). "RBM15 exhibits advantages as a therapeutic target due to its RNA substrate specificity and tumor-selective expression." (PMID 41403702, 2025). "Collectively, RBM15 integrates m6A-dependent and -independent mechanisms with epitranscriptomic and epigenetic networks, establishing itself as a central hub in tumor progression." (PMID 41403702, 2025). "The results revealed that either RBM15 or TNFSF9 mRNA were indeed highly expressed in the tumor tissues of PTX-resistant patients." (PMID 40830812, 2025). "Functional experiments demonstrate that RBM15 silencing suppresses proliferation, migration, invasion, and immune modulation, while inhibiting tumor growth in vivo." (PMID 41403702, 2025). "By modulating this process, RBM15 indirectly enhances the activity of signaling pathways that drive tumor growth and metastasis." (PMID 41403702, 2025). "In vivo, RBM15 depletion significantly delayed tumor progression and enhanced CD8+ T cell infiltration and activation in the tumor microenvironment." (PMID 40370450, 2025). "In vitro and in vivo studies confirm the tumor-suppressive effects of resveratrol, suggesting its potential as a therapeutic agent targeting RBM15-dependent pathways in ccRCC." (PMID 41403702, 2025). "To investigate the alterations in the tumor immune microenvironment induced by RBM15, we performed multicolor flow cytometry analysis along with multiplex immunofluorescence (mIHC) to assess immune cell infiltration in mouse tumors." (PMID 40370450, 2025). "RBM15 plays a pivotal role in tumor immune regulation by modulating immune cell functions and remodeling the TME through multiple mechanisms." (PMID 41403702, 2025). "Such precise regulation of RBM15 expression and activity across distinct cancer types ultimately drives tumor initiation and progression." (PMID 41403702, 2025). "Mechanistically, RBM15 depletion increases the expression of fumarate hydratase (FH), which in turn decreases the level of fumarate, a known suppressor of anti-tumor immunity." (PMID 40370450, 2025). "Emerging evidence indicates that RBM15 regulates tumor cell proliferation, migration, invasion, and metabolic reprogramming through modulation of RNA stability, splicing, and translation." (PMID 41403702, 2025). "Our findings thus are significant because they connect the tumor-intrinsic functional role of RBM15 to the anti-tumor immune responses." (PMID 40370450, 2025). "Our research demonstrated that RBM15 downregulation inhibits NSCLC tumor growth, reduces Ki67 positivity, and suppresses lung and liver metastasis." (PMID 39716068, 2024).
tumor (continued). "This review briefly outlines the structure and operational mechanism, and delineates the unique role of RBM15 in various cancers, shedding light on its molecular basis and providing a groundwork for potential tumor-targeted therapies." (PMID 38915367, 2024). "The genes Herc6, Kat7, Mef2c, Rbm15, and Shld3 were found to be upregulated in both the right and left tumors of the treated groups, suggesting a coordinated response in tumor inhibition." (PMID 39339213, 2024). "In this review, we will focus on the individual function of RBM15 and its related mechanisms, highlighting the current status of RBM15 regulatory mechanisms in tumors and providing researchers with new ideas for tumor therapy." (PMID 38915367, 2024). "Our findings revealed that RBM15 downregulation inhibited tumor growth, as evidenced by reduced tumor volume, lower tumor weight, and decreased Ki67 positivity." (PMID 39716068, 2024). "Downregulation of RBM15 inhibited tumor growth, as evidenced by reduced tumor volume, decreased weight, and a lower Ki67 positivity rate (p < 0.05)." (PMID 39039611, 2024). "Expression analysis of the excised tumor tissues revealed that compared to the sh-NC group, the sh-RBM15 group exhibited decreased expression of RBM15, KDM5B, and KCNQ1OT1, and increased expression of FER1L4 (p < 0.01)." (PMID 39039611, 2024). "In this study, we confirmed that upregulated circ‐CTNNB1 exerted an oncogenic role in OS tumour progression in a RBM15‐dependent manner." (PMID 36181462, 2023). "For the in vivo assay, the tumor volumes were drastically diminished by RBM15 silencing in CRPC cells, and the decreases were restored by AZGP1P2 knockdown." (PMID 37854295, 2023). "Knockdown of RBM15 in CC has been shown to suppress tumor cell proliferation, invasion, and migration as well as the JAK-STAT signaling pathway." (PMID 37474926, 2023). "In our study, we discovered that RBM15 functions as a tumor oncogene in CC, and knockdown of RBM15 inhibits cell proliferation, migration, and invasion, as well as tumor growth in vivo." (PMID 37474926, 2023). "In this study, based on data from the TCGA-THCA cohort, we obtained DEGs between normal and tumor tissues and identified 3 m6A-related genes (KIAA1429, RBM15, and FTO) to construct a risk model and verified its credibility." (PMID 36389678, 2022). "Previous studies showed that the expression of m6A writers (METTL3, RBM15, WTAP), eraser (FTO, ALKBH5) and reader (YTHDF3, YTHDC2) was associated with pathological stage, tumor stage, andprognosis of patients with GC." (PMID 35977935, 2022). "This study aims to analyze the prognostic value of RBM15, and to demonstrate the correlation between RBM15 expression and tumor immunity, as well as to provide clues for further mechanism research." (PMID 35223996, 2022). "In this study, we found that RBM15 mRNA levels were higher in 25 tumor types than in normal tissues." (PMID 35223996, 2022). "In summary, these findings suggest that RBM15 promotes tumor growth in vivo, consistent with in vitro results." (PMID 34707107, 2021). "By comparing 50 normal and 374 tumor tissues, METTL14, YTHDC1, ZC3H13, ALKBH5, YTHDF2, and RBM15 had extremely lower expression in tumor tissues (p < 0.001)." (PMID 34277622, 2021). "The tumor volumes in the RBM15 overexpression group were increased compared to those in the vector group." (PMID 33637103, 2021). "Nude mice xenografts injected with the TU-212 cells revealed that knockdown of TMBIM6 counteracted the effects of increased RBM15 on tumor volumes." (PMID 33637103, 2021). "Consistently, nude mice xenografts injected with the AMC-HN-8 cells revealed that knockdown of RBM15 counteracted the effects of increased TMBIM6 on tumor volumes." (PMID 33637103, 2021). "The most significant positive correlation exists in the writers and the readers' groups, which is consistent with the fact that the expression levels of KIAA1429, YTHDC2, and RBM15 are highly expressed in LUAD tumor tissues." (PMID 32258108, 2020).
tumor (continued). "IHC staining analysis of m6A “writer” suggested that WTAP, KIAA1429 and RBM15/15B expression were upregulated in GC tumor tissues compared with that in normal gastric tissues at protein level, which was consistent with the expression pattern of genes." (PMID 32226518, 2020). "Additionally, in vivo studies further validated that RBM15 facilitated tumor growth by regulating SRSF1." (PMID 40923717, 2026). "Collectively, these results confirmed that RBM15 promoted tumor growth by mediating SRSF1." (PMID 40923717, 2026). "First, RBM15 may act as either an oncogene or tumor suppressor depending on cancer type and context, necessitating detailed characterization of its context-dependent functions." (PMID 41403702, 2025). "Moreover, we further validated that RBM15 content was evidently upregulated in COAD tumor tissues versus normal tissues." (PMID 40883807, 2025). "In vivo experiments confirmed that RBM15 knockdown significantly suppresses tumor growth." (PMID 41403702, 2025). "This indicates that RBM15 not only drives intrinsic malignant behavior of tumor cells but may also promote immune evasion by shaping an immunosuppressive microenvironment, ultimately influencing the efficacy of immunotherapy." (PMID 41403702, 2025). "Therefore, our findings suggest that RBM15 is a promising therapeutic target for enhancing anti-tumor immune responses through metabolic reprogramming." (PMID 40370450, 2025). "Additionally, we conducted a WB assay on the patients’ tumor tissues, which also indicated that the expression of RBM15 and TNFSF9 were drastically upregulated in the PTX-resistant in contrast to the PTX-sensitive group." (PMID 40830812, 2025). "Consistently, RBM15 expression was negatively correlated with tumor purity, suggesting RBM15 may suppress the recruitment of immune cells." (PMID 40370450, 2025). "In addition, the regulation of tumor immune microenvironment by RBM15 is highly environment dependent, and future immune combination strategies require precise tumor typing guidance." (PMID 41256854, 2025). "Furthermore, RBM15 knockdown diminishes the activity of the TGF-β/Smad2 pathway, and pharmacological activation of TGF-β signaling with SRI-011381 reverses the inhibitory effect of RBM15 silencing on tumor cell growth." (PMID 41403702, 2025). "More crucially, we have clearly demonstrated through the use of mice TNBC tumor allograft model experiment that silencing RBM15 could greatly block tumor growth in mice." (PMID 40830812, 2025). "Nevertheless, the connection between RBM15 and FH adds another layer to the understanding of anti-tumor immune responses, by which the m6A writer component suppresses the anti-tumor immunity through regulating key enzymes in carbon metabolism, leading to the release of immunosuppressive metabolites." (PMID 40370450, 2025). "Moreover, Irradiation of 125I seed radiotherapy suppresses glycolysis and tumor growth by inhibiting RBM15/KLF5-mediated m6A modification, thereby reducing proliferation and invasion while promoting apoptosis." (PMID 41403702, 2025). "Emerging evidence suggests that, compared with canonical methyltransferases, RBM15 may exert a more targeted influence on immune cell fate and anti-tumor responses, highlighting its unique and potentially complementary role in shaping tumor immunity." (PMID 41403702, 2025). "By reshaping the TME, RBM15 facilitates immune evasion and drives tumor progression." (PMID 41403702, 2025). "The effect of RBM15/TNFSF9 on PTX sensitivity in vivo was verified by xenograft tumor experiments." (PMID 40830812, 2025). "Modulating RBM15 activity with small-molecule inhibitors or RNA interference could restore the balance between oncogenes and tumor suppressors, thereby inhibiting tumor growth and metastasis." (PMID 41403702, 2025).